IGF1R (insulin like growth factor 1 receptor)
Diseases named in the same sentence as IGF1R in open-access papers (continued):
Sharing a sentence is not in itself a finding about the gene and the disease.
melanoma (continued). "Reduced levels of the receptor tyrosine kinases IGF-1R, FGFR1, PDGFRβ, and EGFR were detected in the RUNX2 knocked down 1205LU melanoma cells as compared with the non-silencing (control) ShRNA-expressing 1205LU cells." (PMID 27102439, 2016). "Regarding resistance to RTK inhibition, we observed that downregulation of IGF-1R and AXL in C8161 melanoma cells expressing ShRUNX2-3 did not result in reduced AKT and ERK phosphorylation but instead increased AKT phosphorylation." (PMID 27102439, 2016). "We also found that RA2 and RA5 decrease IGF-1R mRNA expression in C8161 melanoma cells in contrast to RA2 and RA4, which do not inhibit IGF1R mRNA expression in 1205LU melanoma cells (data not shown)." (PMID 27102439, 2016). "In most patients, melanoma cells exhibited ErbB3/Her3, CD44/Pgp-1, ICAM-1/CD54 and IGF-1-R/CD221, but did not express CD20, ErbB2/Her2, KIT/CD117, AC133/CD133 or MDR-1/CD243." (PMID 24489649, 2014). "Considering the fact that single-agent therapies often do not produce durable responses in melanoma, future therapeutic strategies blocking the IGF-1/IGF-1R axis may need to consider combination therapies." (PMID 36551732, 2022). "Furthermore, it was reported that IGF1R expression correlates with melanoma progression, although early observation indicates the absence of IGF-1 expression in melanoma cells." (PMID 33918490, 2021). "However, no synergic effect of IGF-1R neutralization was observed in the IGF-1dull clone, suggesting the possible involvement of other regulatory factors in melanoma stemness behavior." (PMID 27764776, 2016).
hepatocellular carcinoma (137 papers, 2011 to 2026). A malignant tumor that arises from hepatocytes. "As shown in hepatocellular carcinoma and Ewing sarcoma cells, knockdown of IGF2BPs is associated with downregulation of IGF1R mRNA and protein and consequent inhibition of in vitro cell viability, proliferation, clonogenicity and migration." (PMID 33673232, 2021). "This was noted in hepatocellular carcinoma lines, in which resistance to anti-IGF-1R treatment was associated with increased signaling through EGFR pathways, and that this resistance was overcome by targeting both IGF-1R and EGFR." (PMID 23548153, 2013). "IGF/IGF-1R is upregulated in hepatocellular carcinoma (HCC) and is associated with tumorigenesis." (PMID 33511137, 2020). "Inhibition of IGF-1R (using IGF-1R inhibitors NVP-AEW541 or PPP [picropodophyllin]) combined with sorafenib increases apoptosis in hepatocellular carcinoma cells, demonstrating the role of IGF-1R in sorafenib resistance." (PMID 40283927, 2025). "Recent studies have demonstrated that NEAT1 promotes the proliferation of hepatocellular carcinoma cells and reduces apoptosis by regulating the Let‐7b‐IGF‐1R axis." (PMID 40530890, 2025). "In hepatocellular carcinoma, overexpressing IGF1R promotes cell proliferation, migration, and antiapoptosis through the PI3K/AKT and extracellular regulated protein kinase pathways, contributing to sorafenib resistance." (PMID 38292328, 2024). "In hepatocellular carcinoma, IGF1R activates the downstream SRC signaling pathway to enhance the adhesion ability of hepatocellular carcinoma cells by increasing the phosphorylation level of FAK." (PMID 38292328, 2024). "This study showed that IGF-1R can decrease the response of hepatocellular carcinoma to sorafenib through PI3K / Akt and Ras / Raf / ERK signaling pathways." (PMID 36698167, 2023). "In particular, it binds to, and directly regulates, the insulin-like growth factor 1 receptor (IGF1R) gene in hepatocellular carcinoma." (PMID 35741700, 2022). "In hepatocellular carcinoma, the replenishment of miR-486-5p blocks the IGF-1R pathway by acting on the downstream mediators such as mTOR, STAT3, and c-myc." (PMID 35337095, 2022). "MicroRNA-223 is also involved in regulating the hepatoma cell proliferation through affecting IGF-1R or regulated the metastasis of cervical carcinoma by modulating epithelial-mesenchymal transition." (PMID 35075362, 2022). "EGCG also inhibited the growth of the human hepatoma cell line HepG2 by inhibiting the phosphorylation of insulin-like growth factor-1 receptor (IGF-1R) and reducing the activation of its signaling molecules, such as ERK, STAT-3, Akt and GSK-3β." (PMID 35873545, 2022). "miR-99a, miR-503, and miR-1275 contribute to the pathogenesis of polycystic ovary syndrome, coronary heart disease, and hepatocellular carcinoma by affecting IGF-1R levels." (PMID 33768092, 2021). "A study reported activation of the PI3K/Akt pathway and the RAF/MEK/ERK pathway through caveolin 1 induced overexpression of IGF1R, thus promoting anchorage independence of hepatocellular carcinoma (HCC)." (PMID 33854965, 2021). "MSC EVs overexpressing miR-122 were used to downregulate domain-containing protein 10 (ADAM10), insulin-like growth factor 1 receptor (IGF1R), and cyclin G1 (CCNG1), three proteins implicated in hepatocellular carcinoma." (PMID 34830787, 2021). "A circRNA derived from backsplicing of the IGF1R itself, named circIGF1R, is detectable in hepatocellular carcinoma clinical specimens and promotes cell proliferation by activating the PI3K/Akt pathway." (PMID 33673232, 2021). "For example, circ-IGF1R promoted the proliferation and blocked the apoptosis of hepatocellular carcinoma cells through activating PI3K/AKT pathway." (PMID 32782441, 2020). "Knockdown of Cav1 reduces e.g. IGF1 signaling in H9C2 rat cardiomyoblasts whereas Cav1 overexpression significantly increases IGF1-induced internalization of IGF-1R in human hepatocellular carcinoma cells." (PMID 32458278, 2020).
hepatocellular carcinoma (continued). "Overexpression of miR-29a directly suppressed IGF-1R in the HepG2 Hepatocellular Carcinoma cell-line." (PMID 32211051, 2020). "MiR-342-3p directly targets the 3′UTR of IGF-1R (insulin-like growth factor receptor) acting as a potent tumour suppressor in hepatocellular carcinoma through inhibition of IGF-1R-mediated PI3K/Akt/GLUT1 signalling pathway." (PMID 31212911, 2019). "In contrast to SPARC, GRP78, which is often upregulated on the cell surface in malignancy, can interact with PI3K, CRIPTO, IGF1-R in the breast, prostate, and hepatoma cells, respectively, to promote oncogenic events." (PMID 31243264, 2019). "In advanced hepatocellular carcinoma, activation of IGF1R by ectopic down-regulation of miR-122 counteracted the effects of sorafenib-induced apoptosis, thus conferring sorafenib resistance." (PMID 29642855, 2018). "On the other, 2-FAA-induced, rat hepatoma model, dynamic expression and alterations in IGF1R and IGF1R mRNA, were observed in different stages of malignant transformation." (PMID 29702590, 2018). "Activation of IGF1R signaling pathway promotes proliferation, survival and migration of the hepatoma cells." (PMID 29702590, 2018). "HCC (Hepatocellular Carcinoma) cells exhibited strong gefitinib resistance and the levels of phosphorylation in IGF1R and AKT were dramatically increased after drug treatment." (PMID 29642855, 2018). "Recently, it has been reported that miR-342-3p modulated glycolysis by altering glucose uptake, lactate generation and extracellular acidification rate by suppressing IGF-1R-mediated PI3K/AKT/GLUT1 signaling pathway in hepatoma cells." (PMID 30115973, 2018). "For instance, the kinase IGF1R and protease MMP2 were involved in 650 cases of motif V. MMP2 is located in the downstream of IGF1R-induced signaling pathway, and the inhibition of IGF1R will affect the dissemination of hepatocellular carcinoma (HCC) cells." (PMID 26853265, 2016). "Effects of EGCG on activity of IGF/IGF-1R axis in HepG2 human hepatocellular carcinoma cells was determined and results confirmed that treatment of HepG2 cells with EGCG-induced apoptosis caused a decrease in the p-IGF-1R protein." (PMID 25977926, 2015). "Intriguingly, to overcome IGF-1R inhibition, hepatoma cells were able to activate ErbB3 in an EGFR-dependent manner." (PMID 26729094, 2015). "microRNA-100 promotes the autophagy of hepatocellular carcinoma cells by inhibiting the expression of mTOR and IGF-1R." (PMID 25877859, 2015). "A growing body of evidences suggests an increase in IGF1R expression in human cirrhotic liver, hepatoma cell lines and HCC." (PMID 25225571, 2014). "In the present study, we demonstrated that figitumumab possesses a high affinity for IGF1R/IR heterodimeric receptors as well as IGF1 homodimer receptors and inhibits the IGF/IGF1R signaling axis in gastric cancer and hepatocellular carcinoma cells." (PMID 22438913, 2012). "Targeting IGF-1R by miR-223 was not only seen in HeLa cells, but also in leukemia and hepatoma cells." (PMID 22073238, 2011). "In SMMC-7721, BEL-7404, or Huh-7 hepatoma cells infected with miR-223 constructs, all the cell growth rates slowed down and the expression level of IGF-1R was significantly inhibited." (PMID 22073238, 2011). "In support of this, IGF1R blockade results in decreased hepatoma cell migration in vitro." (PMID 40115165, 2025). "The Editorial Office has been made aware of potential issues surrounding the scientific validity of this paper “MiR-505 suppressed the growth of hepatocellular carcinoma cells via targeting IGF-1R” DOI: 10.1042/BSR20182442, hence has issued an expression of concern to notify readers." (PMID 39526366, 2024). "Additionally, miR-16-5p inhibits the invasion and migration of hepatocellular carcinoma cells by directly targeting the insulin-like growth factor 1 receptor." (PMID 36984512, 2023).
hepatocellular carcinoma (continued). "Overexpression of miR-342-3p has been shown to suppress proliferation, migration, and invasion by targeting FOXM1 in cervical cancer and has also been shown to suppress hepatocellular carcinoma proliferation through the inhibition of the IGF-1R-mediated Warburg effect." (PMID 37958433, 2023). "In addition, KCNQ1OT1 can competitively target miR-148a-3p and consequently promote the expression of the miR-148a-3p target IGF1R gene in hepatocellular carcinoma cells." (PMID 35498136, 2022). "Similarly, in our earlier experiments we found that addition of human recombinant decorin to the Hep3B hepatoma cell line provoked activation of IGF-1R and insulin receptors and massive Akt activation." (PMID 32477937, 2020). "Moreover, miR-16 deters migration and invasion by inhibiting insulin-like growth factor 1 receptor (IGF1R) expression in hepatocellular carcinoma." (PMID 33066509, 2020). "Thus, we detected the expression of IGF1R, and its downstream genes and apoptosis‐associated proteins, in gain and loss of GSTZ1‐1 hepatoma cells." (PMID 31267557, 2019). "On the other hand, elevated levels of tissue expression of IGF2, IGF1R or other IGF system components (IGFBP7), may indicate an increased risk of hepatocellular carcinoma." (PMID 29702590, 2018). "The insulin-mimetic ability of Cu2+ and Zn2+ to activate the PI3K/Akt pathway by the interaction with insulin-receptor (IR) and IGF1-receptor (IGF1R) in HepG2 human hepatoma cells, which result in the phosphorylation and nuclear exclusion of transcription factor FoxO1a, has been recently questioned." (PMID 28090201, 2016). "Based on earlier findings on the role of IGF1 in low-grade ovarian carcinomas, as well as in in vitro studies in hepatocellular carcinoma, a phase II clinical trial is currently underway using the IGF-1R/IR dual receptor tyrosine kinase inhibitor OSI-906 (clinicaltrials.gov)." (PMID 24237932, 2013). "In order to define biomarkers for predicting successful IGF1R targeted therapy, we evaluated the anti-proliferation effect of figitumumab (CP-751,871), a humanized anti-IGF1R antibody, against nine gastric and eight hepatocellular cancer cell lines." (PMID 22438913, 2012). "In hepatocellular carcinoma (HCC), the overexpression of IGF1R is recognized as a key driver of EMT, significantly enhancing the migratory and invasive capabilities of cancer cells." (PMID 39744436, 2025). "After thorough analysis, IGF1R expression was substantially elevated in hepatocellular carcinoma (HCC) tissues compared to normal liver tissues, as demonstrated by the UALCAN database." (PMID 40530890, 2025). "This study investigated the effect and mechanism of IGF-1R in mediating the desensitization of hepatocellular carcinoma (HCC) to sorafenib." (PMID 36698167, 2023). "Combined with the previous studies that miR‐122‐5p affects IR in hepatocytes by targeting IGF‐1R and miR‐182‐5p inhibits IGF‐1R expression in hepatocellular carcinoma, we conjectured that miR‐182‐5p may regulate hepatic IR by binding to IGF‐1R, which was then confirmed by our experimental results." (PMID 38018594, 2023). "Notably, there was a distinctive positive correlation between the plasma GPC3 level in hepatocellular carcinoma patients and the concentration of IGF-1R which means targeting of GPC3/IGF-1 axis could be used to treat HCC." (PMID 37305177, 2023). "In cancer cells, DLEU1 (lncRNA deleted in lymphocytic leukemia 1) could serve as an oncogenic lncRNA that promotes hepatocellular carcinoma tumorigenesis by acting as a ceRNA to regulate the expression of IGF-1R and its downstream PI3K/AKT signaling pathway genes by directly sponging miR-133a." (PMID 33419093, 2021). "Results from experiments in cervical, renal, non-small-cell lung, osteosarcoma, and hepatocellular cancer cells show that miR-497-5p regulates cell growth and proliferation and is associated with the MAPK pathway by targeting several involved genes such as RAF1, KDR/VGFR-2, and IGF1-R." (PMID 33374439, 2020).
hepatocellular carcinoma (continued). "Persistent activation of IGF1R/mTOR signaling pathway plays crucial role in the development of hepatocellular carcinoma (HCC)." (PMID 28624790, 2017). "Deregulation of mTOR and IGF pathways is frequent in hepatocellular carcinoma (HCC), thus mTOR and IGF1R represent suitable therapeutic targets in HCC." (PMID 26756219, 2016). "Moreover, induction of cell cycle arrest by miR-99a may suppress expression of insulin-like growth factor 1 receptor (IGF-1R) and mammalian target of rapamycin (mTOR) in hepatocellular carcinoma cells." (PMID 24637915, 2014). "However, in hepatocellular carcinoma cells the scenario observed seems to be the contrary, since the epithelial phenotype was strongly associated with expression of IGF-2 and IR as well as activation of IGF-1R and IR." (PMID 24282611, 2013). "miR-486-5p targets and downregulates the insulin-like growth factor-1 receptor (IGF-1R), a key regulator of hepatocellular carcinoma progression." (PMID 40510336, 2025). "Ceritinib has demonstrated antitumor activity in hepatocellular carcinoma cells by inhibiting the ALK and insulin-like growth factor 1 receptor (IGF1R) signaling pathways." (PMID 38399413, 2024). "Since IGF-1R and YAP were both upregulated in sorafenib-resistant hepatocellular carcinoma (HCC), we investigated the interplay between IGF-1R and Hippo-YAP pathway in BCSCs." (PMID 37081542, 2023). "Almost half of these genes (purple-colored genes) were enriched in Hepatitis B, Hepatitis C and Hepatocellular carcinoma pathways including MYC, CD81, CDKN1A, IGF1R and so on which were reported in Hepatocellular carcinoma." (PMID 37051592, 2023). "By directly increasing PTK2 and IGF1R in hepatocellular carcinoma cells, BACH1 speeds up the development and spread of Hepatocellular carcinoma (HCC)." (PMID 36407100, 2022). "GRK2 has been shown to negatively regulate the insulin-like growth factor-1 receptor (IGF1-R) signaling involved in proliferation and migration by decreasing cyclin in human hepatocellular carcinoma HepG2 cells." (PMID 33806057, 2021). "Being up-regulated in hepatocellular carcinoma cells, miR-155 can increase expression of IGF-II and IGF-1R, while decreasing IGFBP-3 expression." (PMID 33768092, 2021). "Increasing evidence shows that IGF1R and its ligands (IGF‐1, IGF‐2) play an important role in the development and progression of several cancers, including hepatocellular carcinoma (HCC)." (PMID 31267557, 2019). "IGF1R and its substrates, IRS1 and IRS2, were overexpressed in five human hepatoma cell lines (HepG2, Hep3B, HuH7, HuH6, and PLC/PRF5)." (PMID 29702590, 2018). "miR-486-5p was recognized as a direct regulator of insulin-like growth factor-1 receptor (IGF-1R), a modulator of hepatocellular carcinoma." (PMID 30306093, 2018). "Focusing on IGF/IGF-1R signaling, in vitro treatment with EGCG reduced IGF-1 and the activated form of IGF-1R levels and increased IGFBP-3 in human hepatoma and colon cancer cells, indicating that EGCG exhibited inhibitory actions on the IGF/IGF-1R axis." (PMID 30205425, 2018). "Two of these potential target genes, stathmin (STMN1) and the insulin-like growth factor 1 receptor (IGF1R), attracted attention because both have been reported to be the target genes of miR-223 in hepatocellular carcinoma and cervical cancer." (PMID 27441818, 2016). "The present study explored the role of IGF-1R in the development and progression of hepatocellular carcinoma (HCC) and the possibility of IGF-1R silencing by lentivirus-mediated RNA interference (RNAi) as a therapeutic target for HCC." (PMID 27813495, 2016). "In hepatocellular carcinoma, the IGF-2/IGF-1R signal was shown to be involved in Nanog-mediated self-renewal of hepatic CSCs." (PMID 23663564, 2013). "In hepatoma cell lines, 2 hour incubation with IMC-A12 completely blocked downstream signalling of IGF-1R as shown by the suppression of phosphorylated AKT and phosphorylated S6 kinase." (PMID 21729319, 2011).